MTOR (mechanistic target of rapamycin kinase)
Diseases named in the same sentence as MTOR in open-access papers (continued):
Sharing a sentence is not in itself a finding about the gene and the disease.
megalencephaly (15 papers, 2015 to 2024). A congenital abnormality in which the occipitofrontal circumference is greater than two standard deviations above the mean for a given age. "Seizure related death was reported in a patient with mTOR pathway-associated megalencephaly, and thus development of a specific therapeutic intervention is crucial." (PMID 28086757, 2017). "We report the mTOR activator gene RHEB as an ID gene that is associated with megalencephaly when mutated." (PMID 29051493, 2017). "Elucidation of the molecular mechanisms underlying megalencephaly is crucial to determine the value of investigating therapeutic agents, such as rapamycin, in the context of mTOR pathway-associated megalencephaly." (PMID 28086757, 2017). "Here, we have successfully established a combination of genetic and biochemical methods for diagnosis of mTOR pathway-associated megalencephaly, and have attempted to delineate the clinical characteristics of the disorder." (PMID 28086757, 2017). "In this study, we conducted genetic and biochemical analyses in 13 patients with increased head circumference and neurological symptoms such as developmental delay and epilepsy, and investigated clinical features and imaging of mTOR pathway-associated megalencephaly." (PMID 28086757, 2017). "A combination of genetic and biochemical methods successfully identified mTOR pathway involvement in nine of 13 (approximately 70%) patients with megalencephaly, indicating a major contribution of the pathway to the pathogenesis of megalencephaly." (PMID 28086757, 2017). "In addition, the present results indicate that defects in the mTOR signalling pathway lead to the abnormal enlargement of the brain, megalencephaly." (PMID 34576223, 2021). "However, the prevalence of mTOR pathway involvement in patients with megalencephaly remains to be elucidated." (PMID 28086757, 2017). "A combination of genetic and biochemical methods was able to identify the involvement of the mTOR pathway in approximately 70% of patients with megalencephaly of an unknown etiology." (PMID 28086757, 2017). "In this study, we identified constitutive activation of the mTOR pathway in nine of 13 patients with megalencephaly of unknown etiology, indicating a significant role for the mTOR pathway in pathogenesis of genetic megalencephaly syndromes." (PMID 28086757, 2017). "We were struck by the apparent recurrence of mTOR-related mutations in ID, the persistent co-morbid megalencephaly and the absence of studies investigating the overall contribution of the mTOR pathway to ID and brain growth." (PMID 29051493, 2017). "Thus, the mTOR pathway associated-megalencephaly, a disease for which there is no curative treatment available, could also be a therapeutic target." (PMID 28086757, 2017).
primary effusion lymphoma (15 papers, 2014 to 2025). A large B-cell lymphoma located in the body cavities, characterized by pleural, peritoneal, and pericardial fluid lymphomatous effusions and that is always associated with human herpes virus-8 (HHV-8). "It has been indicated that quercetin suppresses STAT3 and PI3K/AKT/mTOR pathways in primary effusion lymphoma (PEL) cells leading to downregulate the prosurvival cellular proteins expression, including cMyc, cyclin D1, and c-FLIP." (PMID 32175075, 2020). "The mTOR inhibitor Everolimus proved to be extremely promising, both in terms of KS and primary effusion lymphoma (PEL)." (PMID 39772235, 2024). "PI3K/AKT/mTOR, Wnt/β-catenin, and STAT3 also participated in quercetin-induced cell death in primary effusion lymphoma (PEL)." (PMID 33494431, 2021). "In hyperactive primary effusion lymphoma (PEL), quercetin reduced the release of cytokines and inhibited PI3K/Akt/mTOR and STAT3 pathway-induced autophagy, ultimately resulting in PEL cell death." (PMID 34025409, 2021). "Primary effusion lymphoma (PEL) displays activated PI3K/Akt/mTOR signaling." (PMID 32410999, 2020). "In primary effusion lymphoma (PEL) cells, metformin inhibits both mTOR and STAT3 pathways by decreasing intracellular ROS levels." (PMID 29554968, 2018). "Additionally, quercetin inhibits PI3K/AKT/mTOR and STAT3 pathways specifically in primary effusion lymphoma (PEL) cells, leading to downregulation in the expression of the pro-survival cellular proteins such as c-FLIP, cyclin D1, and c-Myc." (PMID 35956766, 2022). "We have recently shown that quercetin, a flavonoid with anti-inflammatory and antioxidant properties and anti-cancer potential, was able to inhibit multiple pro-survival pathways activated in primary effusion lymphoma (PEL) cells, including STAT3, mTOR, and NF-κB, reducing cell survival." (PMID 31547402, 2019). "Quercetin exhibits anticancer effects in primary effusion lymphoma (PEL) by reducing cytokine release and inhibiting PI3K/Akt/mTOR and STAT3 pathway-induced autophagy, leading to PEL cell death." (PMID 41294806, 2025). "The activation of mTOR represents a mechanism of resistance of primary effusion lymphoma (PEL) cells undergoing DMF treatment, even if this molecule can still impair PEL survival." (PMID 36614036, 2022).
acute promyelocytic leukemia (14 papers, 2012 to 2025). An aggressive form of acute myeloid leukemia (AML), characterized by arrest of leukocyte differentiation at the promyelocyte stage, due to a specific chromosomal translocation t(15;17) in myeloid cells. "They observed that Tanshinone IIa induces autophagy and apoptosis in acute promyelocytic leukemia NB4 cells through the downregulation of the PI3K/AKT/mTOR pathway." (PMID 40917720, 2025). "All-trans retinoic acid’s action against acute promyelocytic leukemia is probably related to promoting the transcriptional activation of genes related to the differentiation and regulation of autophagy through the inhibition of the mammalian target of rapamycin (mTOR)." (PMID 40944112, 2025). "In acute promyelocytic leukemia, tan IIA blocked the PI3K/Akt/mTOR axis and promoted autophagy of NB4 cells, decreasing PI3K, Akt, and mTOR protein levels while raising p-ULK-1 and LC3B levels." (PMID 37964867, 2023). "RA can be used for the treatment of acute promyelocytic leukemia (APL) and plays its anti-APL effects by inhibiting mTOR signaling." (PMID 37369771, 2023). "In another report, the dysregulation of basal DDIT4 gene expression in several cancer types (e.g. lung, breast, prostate) can be altered by promyelocytic leukemia (PML) and lead to mTOR activation and cancer progression." (PMID 32497068, 2020). "Moreover, arsenic trioxide-induced autophagy through inhibiting the mTOR pathway contributes to degradation of the PML/RARA fusion protein in acute promyelocytic leukemia (APL)." (PMID 22829831, 2012).
cerebral infarction (14 papers, 2015 to 2026). An ischemic condition of the brain, producing a persistent focal neurological deficit in the area of distribution of the cerebral arteries. "Luteolin enhances cell viability and inhibits apoptosis by downregulating the matrix metalloproteinase 9 expression and activating the PI3K/AKT-mediated mTOR and GSK3β pathways, which alleviate cerebral infarction." (PMID 35712089, 2022). "In this study, 3-MA, LEU, and rapamycin were used to analyze the role of artesunate, and it was found that mTOR was mediated in the autophagy of cerebral infarctions." (PMID 30174640, 2018). "This study suggests that p-mTOR acts as a potential biomarker of brain infarctions, and artesunate provides a potential role for the therapy of ischemic brain infarctions." (PMID 30174640, 2018). "Previous studies have reported that mTOR overactivation increases the cerebral infarct size, and a decrease in mTOR activity reduces inflammation and nerve tissue damage and facilitates motor recovery after an ischemic event." (PMID 26042033, 2015). "The aims were to explore the mechanism of mTOR on autophagy and determine whether artesunate affects cerebral infarction by regulating the expression of mTOR and autophagy." (PMID 30174640, 2018). "This study suggests that hypoxia-induced brain infarctions significantly increase the expression of p-mTOR, Artesunate administration seems to protect the brain against infarction by decreasing the expression of mTOR, while the protectiveness is reversed by LEU and 3-MA." (PMID 30174640, 2018). "Resveratrol improves neurological function and alleviates neurological damage in cerebral infarction, inhibits apoptosis, and protects hippocampal neurons from damage induced by I/R injury via activation of the Janus kinase 2 (JAK2)/PI3K/AKT/mTOR pathway." (PMID 35712089, 2022). "In addition, Ang II increased the area of cerebral infarction, promoted neuronal degeneration and apoptosis, aggravated neurological deficits on righting and geotaxis reflexes, and was accompanied by increased expressions of phosphorylated GSK-3β and mTOR." (PMID 33425219, 2020).
chronic obstructive pulmonary disease (14 papers, 2016 to 2024). A chronic and progressive lung disorder characterized by the loss of elasticity of the bronchial tree and the air sacs, destruction of the air sacs wall, thickening of the bronchial wall, and mucous accumulation in the bronchial tree. "Some clues came from a recent study which found higher plasma BCAA levels may be associated with cardiac arrhythmias via mTOR pathway." (PMID 36845444, 2023). "Interestingly, mTOR signaling has also been linked to cigarette-induced chronic obstructive pulmonary disease (COPD) and emphysema." (PMID 38541642, 2024). "The PI3K/AKT/mTOR pathway is claimed to regulate autophagy to induce apoptosis of alveolar epithelial cells in chronic obstructive pulmonary disease and modulate the clearance of protein to aggregate the neurodegeneration." (PMID 34738222, 2022). "Lending credence to the involvement of mTOR in chronic lung disease, a recent study supports that mTOR activation drives pneumocyte senescence and contributes to inflammation in a mouse model of chronic obstructive pulmonary disease." (PMID 29518028, 2018). "mTOR is a potential therapeutic target in chronic obstructive pulmonary disease COPD." (PMID 32534452, 2020). "Smoking can induce downregulation of PTEN expression (likely due to an immune-mediated mechanism) and accordingly increase mTOR/Akt signaling activation in airway epithelium of healthy and chronic obstructive pulmonary disease (COPD) smokers compared to non-smokers." (PMID 31404976, 2019).
colorectal adenocarcinoma (14 papers, 2019 to 2026). The most common type of colorectal carcinoma. "As an example, the synergistically efficacious combination of dexamethasone (agonist of the glucocorticoid receptor) and mk-8669 (PI3K/mTOR dual inhibitor) in a colorectal adenocarcinoma cell-line is masked by HSA due to antagonistic potency." (PMID 34326325, 2021). "PI3K/Akt, and mTOR have been found to be over-activated in colorectal adenocarcinoma and have become potential targets for treatment." (PMID 31871431, 2019). "NVP-BEZ235, a dual PI3K/mTOR inhibitor, showing great therapeutic potential in colorectal adenocarcinoma and prostate cancer." (PMID 31871431, 2019). "AK5 expression regulates AMPK/mTOR signalling and may be closely related to metastasis in colorectal adenocarcinoma." (PMID 34135408, 2021). "This research investigated the impact of WJ-CM on HT-29 colorectal adenocarcinoma cells by examining autophagy biomarkers and the AMPK/mTOR pathway." (PMID 41346764, 2026). "Phosphorylated mTOR was positively correlated with plateletcrit (PCT), sodium, and metastasis of colorectal adenocarcinoma." (PMID 39337548, 2024). "The expression of miR-34b in colorectal adenocarcinoma tissue was negatively correlated with the expression of p-PI3K, p-AKT, and mTOR proteins." (PMID 37443682, 2023).
Cowden syndrome (14 papers, 2015 to 2025). "High levels of dysregulated mTOR activity have been associated with PTEN-related diseases including Cowden Syndrome." (PMID 26798346, 2015). "Another subset of NET patients are genetically predisposed to mammalian/mechanistic target of rapamycin (mTOR) pathway dysregulation, due to suffering from tuberous sclerosis complex (affecting TSC1, TSC2) or Cowden syndrome (affecting PTEN)." (PMID 39456803, 2024). "Mutations in PTEN, which suppresses the mTOR pathway, are also found in PTEN hamartoma syndrome, such as Cowden disease, Bannayan syndrome, and Proteus syndrome." (PMID 28086757, 2017). "An increased Akt/mTOR activity is consistent with deficiencies of FMR1, TSC1/2, or PTEN found in Fragile X, TSC, and Cowden syndrome, respectively." (PMID 28361047, 2017). "Cowden Syndrome is associated with loss-of-function mutations in the tumor suppressor gene PTEN, a component of the mammalian target of rapamycin (mTOR) pathway that plays a central role in controlling cell growth, proliferation, and metabolism." (PMID 26798346, 2015). "Animal studies suggest that pharmacological mTOR inhibition may promote regression of advanced mucocutaneous Cowden's disease-like lesions and inhibit tumor growth of pulmonary carcinoid." (PMID 26798346, 2015). "Increased Akt/mTOR activity is consistent with deficiencies of FMR1, TSC1/2, or PTEN found in Fragile X, TSC, and Cowden syndrome and suggests that increased Akt/mTOR activity may have a role in the pathophysiology of the general ASD population and not limited to single ASD genetic mutations." (PMID 28361047, 2017). "Furthermore, studies are needed to explore whether mTOR inhibition represents a therapeutic option for the treatment of both Cowden Syndrome and pulmonary carcinoid NETs." (PMID 26798346, 2015).
follicular lymphoma (14 papers, 2014 to 2025). Follicular lymphoma is a form of non-Hodgkin lymphoma characterized by a proliferation of B cells whose nodular structure of follicular architecture is preserved. "Oncogenic RRAGC (Rag guanosine triphosphatase C) mutations identified in patients with follicular lymphoma facilitate the interaction between Raptor (regulatory protein associated with mTOR) and Rag GTPase." (PMID 37749558, 2023). "Recent evidence in follicular lymphoma further demonstrates that activating mutations in STAT6 sensitize tumor cells to IL-4, driving downstream mTOR pathway activation and compensating for CREBBP deficiency." (PMID 40864740, 2025). "A phase II clinical trial demonstrated that treatment with the mTOR inhibitor voxtalisib achieved satisfactory efficacy in patients with follicular lymphoma." (PMID 32645691, 2020). "CLL samples with mutations of the transcriptional cofactor CREBBP, known as a key driver in follicular lymphoma, were more sensitive to the mTOR inhibitor everolimus." (PMID 29227286, 2018). "AKT1-independent activation of mTOR has been reported in several cell types, including B-lymphocyte cell lines and follicular lymphoma cells." (PMID 25769101, 2015). "The PKCζ/mammalian target of rapamycin (mTOR) pathway may also be a therapeutic target for rituximab-mediated treatment of follicular lymphoma." (PMID 36358843, 2022). "Moreover, we observed that in AT-1 cells, the inhibition of SYK by entospletinib generally downregulates the mTOR pathway, as already described in follicular lymphoma and B-ALL cells." (PMID 31817853, 2019). "While PI3K/Akt/mTOR inhibitors have been effective treating other hematological malignancies, such as chronic lymphoblastic leukemia (CLL) and follicular lymphoma (FL), in AML, the clinical potential of PI3K/Akt/mTOR inhibitors has not yet been fully elucidated." (PMID 32932888, 2020).
gout (14 papers, 2020 to 2025). A condition characterized by painful swelling of the joints, which is caused by deposition of urate crystals. "Moreover, the process of autophagy is governed by PI3K/AKT pathway andmammalian target of rapamycin (mTOR), and it is implicated in the inflammatory response of gouty arthritis." (PMID 38094893, 2023). "Mechanically, MLT‐MLP modulated the metabolic pattern of inflammatory macrophages by inhibiting the mTOR pathway, contributing to its therapeutic effect and providing a promising treatment strategy for gouty arthritis." (PMID 39717013, 2025). "In gout, the drug demonstrated promising results by inhibiting mTOR signalling, reducing inflammatory mediator release, and lowering gout attack frequency in patients with diabetes." (PMID 39463877, 2024). "This comprehensive approach regulates the differentiation of CD4+ T cells through the PI3K/AKT/mTOR cascade and remodels the gut microbiome, offering a strategy for gout treatment." (PMID 38094893, 2023). "The MSU crystal has also been found to activate autophagy with subsequent cell death by inhibiting the phosphorylation of the AKT/mTOR signaling cascade, thereby playing a crucial role in the promotion of gout." (PMID 38094893, 2023). "Additionally, the PI3K/AKT signalling pathway is a primary regulator of NET formation; the total saponin of Dioscorea perforata inhibits neutrophil extracellular trap formation through the PI3K/AKT/mTOR axis, alleviating gouty arthritis in rats." (PMID 41298226, 2025). "Increased expression of mTOR is a signature phenomenon found in gout patients." (PMID 34281285, 2021). "A recent study using a translational approach from ex vivo to in vitro and back to in vivo showed that ex vivo immune cells from gout patients exhibit higher relative gene expression of the mTOR pathway as compared to healthy controls, with monocytes being the most prominent mTOR expressers." (PMID 32899806, 2020). "The declined mTOR pathway could concomitantly inhibit cell growth, enhance autophagy and decrease activation of the NF-κB pathway as well as oxidative stress, thus reducing inflammatory processes and preventing a gout attack." (PMID 33672821, 2021). "Daphnetin, a coumarin derivative, regulates the AMPK/mTOR signaling pathway to inhibit inflammation and promote autophagy in monosodium urate‐induced mice and THP‐1 cells, thereby suppressing MSU‐induced gouty arthritis." (PMID 40304008, 2025). "Therefore, mTOR inhibitor metformin may inhibit the inflammatory process in gout patients." (PMID 34281285, 2021). "In addition, NFIL3 can aggravate the inflammatory response in gout by stimulating neutrophil autophagy and the formation of NETs through REDD1/mTOR." (PMID 36532016, 2022). "Nuclear factor, interleukin 3 regulated (NFIL3), which is highly expressed in neutrophils of patients with gout, promotes its transcription by binding to the REDD1 promoter, which enhances autophagy and NET formation by inhibiting the mTOR pathway, to promote inflammatory responses." (PMID 35464445, 2022). "The increased SUA after fasting for a long term may not induce any gout flares, plausibly as fasting could reduce the signaling pathway of the mammalian target of rapamycin (mTOR)." (PMID 33672821, 2021). "In addition, Cyclocarya paliurus ameliorates hyperuricemia and gout via a mechanism that may involve 3β,23-dihydroxy-12-ene-28-ursolic acid, a potent substance derived from C. paliurus that inhibits NLRP3 inflammasome formation via PI3K/Akt/mTOR-dependent autophagy." (PMID 35464445, 2022).